CD4 (CD4 molecule)
Diseases named in the same sentence as CD4 in open-access papers (continued):
Sharing a sentence is not in itself a finding about the gene and the disease.
tumor (continued). "To analyze whether different drugs can promote the increase of tumor-infiltrating T cells, we examined the proportion of CD4+ and CD8+ T cells, NK1.1, and CD4+Foxp3+ Treg in the spleen of mice." (PMID 35875081, 2022). "To further investigate the mechanism by which tumor-infiltrating lymphocytes were affected by miR-128-3p, we found that miR-128-3p knockdown or overexpression increased or decreased the differentiation of CD4+ CD25+ Foxp3+ Tregs." (PMID 34968167, 2022). "In general, the number of adaptive immune cells, such as activated CD4+ T cells, effector memory CD4+ T cells, type-17 T-helper (Th17) cells, and Th2 cells, in tumor tissue was higher than that in adjacent normal tissue, which indicated an activated immune response in tumor tissue." (PMID 35814465, 2022). "Thus, CAFs have been implicated in the proliferation of CD4+FOXP3+ Treg cells, tumor progression, angiogenesis, and metastasis." (PMID 35464435, 2022). "According to the results, the high-risk group was more negatively associated with tumor-infiltrating immune cells such as CD4+ T cells, hematopoietic cells, no regulatory CD4+ T cells, and neutrophil cells." (PMID 35860590, 2022). "To answer these questions, and further investigate the mechanism of CD4-mediated tumor rejection, we used different bone marrow donor mice to obtain sets of chimera mice that allowed us to separate, at the cellular level, antigen presentation from IFNγ signaling occurrences." (PMID 35903540, 2022). "We, however, cannot exclude that exhausted tumor-infiltrating CD4 T cells do recirculate." (PMID 35954341, 2022). "It is possible that the CD86/CD28 costimulatory signal primarily affected the survival and activation of memory CD4 T-cells, which were associated with OS and RFS and could kill tumor cells." (PMID 35463956, 2022). "A high density of TLSs correlated strongly with a high infiltration of CD8+ T cells and CD4+ T cells in non-small cell lung cancer, which suggests that TLSs may play a key role in shaping the immunological character of the tumour microenvironment." (PMID 35365704, 2022). "Likewise, during tumor expansion, tumor-specific CD4+ T cells lose their anti-tumor activity, whereas an increase in the number of Treg cells is observed." (PMID 36298472, 2022). "Additionally, expression levels of Jun and Fos, transcription factors critical to T cell activation, were elevated in the cytokine producing CD4 and γδ populations potentially indicating a critical role in tumor response." (PMID 35924165, 2022). "Taken together with the results from the preventative setting, these studies collectively indicate that CD4+ T cells play a role in vessel maturation early in tumor development while ICIs act through CD8+ T cells to normalize blood vessels in the treatment setting." (PMID 35712656, 2022). "Besides, tumor-infiltrating lymphocytes can promote anti-tumor immunity, for example, CD4+T cells have cytotoxicity and their combination with CD8+T cells can exert better inhibitory activity on tumor cells." (PMID 35464860, 2022). "We speculated that the antitumor capacity of activated CD4 T cells may be cloaked and limited by senescence phenotype and immunosuppressed molecules on tumor cells (such as PD-L1)." (PMID 36458010, 2022). "In addition, some studies have reported that triptolide can inhibit the expression of interferon-γ (IFN-γ)-induced programmed death-1 ligand-1 (PD-L1) on the surface of tumor cells and reverse the inhibitory effect of tumor cells on CD4+ T cells." (PMID 35443712, 2022). "However, in tumor-free Lyve-1-KO livers numbers of hepatic CD4+, CD8+ and regulatory T cells were increased." (PMID 36496412, 2022). "Noteworthy, FGL1 is positively associated with CD4+ T cell levels within the tumor, while it can also support the expression of CD3D and prevent that of FOXP3; hence, FGL1 may support T cell tumor infiltration and function in the cancer microenvironment." (PMID 36268014, 2022).
tumor (continued). "It was found that RBM38 was related to tumor purity (r = −0.097, p = 0.037), B cell infiltration (r = 0.271, p < 0.001), CD4+ T infiltration (r = 0.264, p < 0.001), neutrophil infiltration (r = 0.132, p = 0.005), and dendritic cell infiltration (r = 0.24, p < 0.001)." (PMID 35326741, 2022). "The pro-tumour function of neutrophils can be implicated in tumour initiation by prostaglandin E2 (PGE2) expression, the promotion of tumour growth by TNF-induced IL-17-producing CD4+ T cells and by matrix metalloproteinase 8 or 9 (MMP8-MMP9 that remodel the ECM and induce angiogenesis." (PMID 35406451, 2022). "Past studies have shown that CD4+ T cells played active roles in anti-tumor immunity." (PMID 35483337, 2022). "This may be especially significant in the context of the tumor immune landscape, where distinct patterns of immune checkpoint expression may influence the tumor-infiltrating CD4+ T cell milieu." (PMID 35523809, 2022). "In addition, CXCL10 can induce CD8+ and CD4+ effector T cells to the tumor site and enhance their function." (PMID 35710862, 2022). "Tumor-infiltrating dendritic cells (DCs) with a deficiency in maturation or antigen-presenting cell function have an immunosuppressive or tolerogenic character, inhibiting CD8+ and CD4+ T-cell priming." (PMID 35392957, 2022). "OAd.TNFa-IL-2 virus also increased CD4/CD8 T cell infiltration in the tumor microenvironment." (PMID 35155581, 2022). "In addition to direct recognition of tumours, CD4 T cells can also be involved in the activation of M1 macrophages and provision of help for CD8 T cells." (PMID 36544781, 2022). "However, higher levels of CD4+ T-cell infiltration were observed in resected tumours that achieved MPR." (PMID 36104359, 2022). "In our PDX model, trametinib induced a more evident fold increase in CD103+CD8+ TRM cells in tumor implants of PDX mice that received RepTILs with high CD4+ TIL numbers, and the transfer of RepTILs rich in CD8+ TILs encompassed an increase in intratumoral TRM cells regardless of trametinib." (PMID 35740548, 2022). "The earliest reports that CD4+ T cells could be directly cytotoxic to tumor cells have been shown in the context of chemotherapy-induced lymphopenia." (PMID 35008422, 2022). "Moreover this study reported that STAT3 inhibition in CD4+ lymphocytes improved the anti-tumor immunity conferred by a lymphocyte adoptive transfer." (PMID 35606804, 2022). "On the other hand, CD4+ Th2 cells, regulatory B cells, CD4+ T regulatory cells, myeloid-derived suppressor cells, and alternatively activated macrophages (M2) are co-opted by the tumour and support tumour development and progression." (PMID 36180554, 2022). "Interestingly, senescence surveillance of pre-malignant cells usually limits cancer development, by activating CD4+ T-cell, which are important for tumour suppression in vivo, representing an extrinsic component of the senescence anti-tumour barrier." (PMID 36712972, 2022). "In our research, we found that the tumor suppressor microenvironment was more serious with BSSs, the ratio of CD4+ and CD8+ was slightly downregulated, and the ratio of Tregs was significantly upregulated, especially for the HTBS and QDBS groups, the proportion of Treg was highest." (PMID 35711625, 2022). "Peripheral-derived γδT cells activated by gastric tumors can not only effectively kill tumor cells, but also induce the activation and proliferation of CD4+ and CD8+αβT cells through the antigen-presenting cell properties of Vγ9Vδ2 T cells, and enhance the cytotoxic function of CD8+αβT cells." (PMID 36685942, 2022). "Since MHC class II-restricted antigens naturally recognized by CD4+ T cells were poorly presented on most tumor cells, CD4+ T cells engineered with an MHC class I-restricted TCR have been evaluated as an attractive strategy to exert antitumor effector functions." (PMID 35928827, 2022).
tumor (continued). "Tumor immune infiltration analysis using TIMER showed that the high-risk group had higher degrees of infiltration for all six immune cell types, namely, CD8 T cells, CD4 T cells, B cells, dendritic cells, macrophages, and neutrophils." (PMID 36330335, 2022). "One alternative mechanism by which tumor cells may overcome cytotoxic CTL-mediated tumor cell death is through downregulation of tumor antigen expression, leading to a reduction in CD4+ T-helper cell activation and active CTLs." (PMID 34918208, 2022). "Thus, a virus-induced FBL3 tumor in mice, which is normally eliminated by CD8+ T cells, was eliminated by tumor-specific CD4+ T cells that were also shown to produce granzyme B, but only in the absence of CD8+ T cells and Tregs." (PMID 36159781, 2022). "CD4+ central memory T cells and eosinophils were expressed significantly lower in tumor cells." (PMID 36134026, 2022). "Furthermore, infiltrating T cells in all tumor samples were largely CD4 T cells, and, surprisingly, very few patients’ tumor samples had CD8 T cell infiltration." (PMID 35662283, 2022). "Although positively correlated with elevated AFP and poor tumor differentiation, CD4+ tumor infiltrating lymphocytes (TILs) are associated with neither overall survival nor disease-free survival." (PMID 35321670, 2022). "A recent study showed that exosomes derived from Vδ2-T cells could promote the expansion of EBV-specific CD4+ and CD8+ T cells and control EBV-associated tumor cells through FasL and TRAIL pathways." (PMID 35632758, 2022). "The hypoxic tumor region can recruit immunosuppressive cells such as myeloid-derived suppressor cells (MDSCs), tumor-associated macrophages (TAMs), tumor-associated neutrophils (TANs) and Tregs and negatively affect the activation of CD8+ T cells and CD4+ T cells." (PMID 36494419, 2022). "Tumor-infiltrating PD1+CD4+ T lymphocytes were higher in patients with local recurrence (p = 0.03)." (PMID 35051220, 2022). "Hence, CD8+ T cells need to receive signals from other immune cells such as CD4+ Th cells to become fully licensed to kill tumor cells." (PMID 35439168, 2022). "Tumor-specific CD4+ T cells express high levels of PD-1 after transferred into tumor-bearing mice; however, it remains to be determined whether CD4+ T-cell adoptive transfer has synergistic effect with ICB." (PMID 35784297, 2022). "Our proposed vaccine, NKT ligand-loaded CD1d+ cells carrying the tumor antigens that target dendritic cells and induces activation of innate immunity and antigen-specific CD4+ and CD8+ T cell responses, named artificial adjuvant vector cells (aAVC), should be efficacious." (PMID 35269735, 2022). "During the course of tumor development, host immune cells such as macrophages, natural killer cells of the innate arm, and cytotoxic T CD8+ and CD4+ cells of the adaptive arm of the immune system recognize antigens expressed on tumor cells and eliminate them, thus preventing development of a tumor." (PMID 34689178, 2022). "Notably, compared with BCG treatment, M. brumae treatment triggered a more immune-active tumor microenvironment, increasing the proportion of total activated immune cells and producing enrichment of activated CD4+ and CD8+ TEM cells." (PMID 36304456, 2022). "We compared the immune repertoire between treatment groups by assessing CD8+ T cells, CD4 + FOXP3+ Tregs, the CD8+ T cell to Treg ratio, CD45 + CD11b + CD103+ dendritic cells, and CD44highCD62Llow effector memory CD8+ and CD4+ T cells in spleen samples from 4T1-luc tumor-bearing mice." (PMID 35681672, 2022). "Tregs are a subset of CD4+ immune T cells that, in physiological conditions, guarantee tolerance to self-antigens and prevent/suppress autoimmune reactions, while, in cancer, they supply tumor progression and tumorigenesis by impairing host immune defenses." (PMID 35053430, 2022).
tumor (continued). "Studies showed that CD4+ T lymphocytes could take on activities in the immune response against tumor by secreting cytokines and activating CD8+ T lymphocytes." (PMID 35694271, 2022). "Additionally, CD4 T cells can exhibit direct cytotoxicity of tumor cells and indirectly kill tumor cells through activation of APCs." (PMID 35565329, 2022). "In our case, reduced expression of CD80 on tumor cells by H89 may reduce the tumor-mediated exhaustion of both CD4+ and CD8+ TLs." (PMID 35572581, 2022). "The nanoparticles could target DCs in the tumor microenvironment, enhance their tumor cell antigen presentation ability, and exert anti-tumor effects by activating both CD4+ and CD8+ T cells." (PMID 36005653, 2022). "Expanding a population of CD4 Th1 cells targeting a shared tumor antigen could lead to intratumoral re-activation of these cells, inducing an inflammatory TME and immune-mediated cancer cell death." (PMID 36089578, 2022). "Flow cytometry analysis also confirmed a decreased proportion of CD4+CD25+CD127− Treg cells in MPR tumor lesions, consistent with the negative association of Tregs to the clinical response to neoadjuvant chemoimmunotherapy." (PMID 35831283, 2022). "The immunosuppressive cells in the TME of PC are mainly tumor associated macrophages (TAMs), myeloid-derived suppressor cells (MDSCs), and tumor-infiltrating lymphocytes (TILs), which are composed of CD4+ T cells, CD8+ T cells, and FOXP3+ regulatory T cells (Tregs)." (PMID 36106025, 2022). "Although long-term αCD4 antibody treatment failed to completely deplete CD4+ T cells in mice, the marked reduction in CD4+ T cells in Tslptg KrasG12D mice erased any differences between tumor size and percentage of lung surface area with tumor in Tslptg KrasG12D compared with KrasG12D mice." (PMID 35565302, 2022). "Administering Lactiplantibacillus plantatum LS/07 repressed the tumor frequency, accompanied by an increase in CD4+ T-cells in tumor tissue, reduction in the serum tumor necrosis factor-α concentration, and elevation in CD8+ T-cell number in tumor tissue but decreased blood CD8+ T-cell count." (PMID 36615662, 2022). "Increased levels of tumor antigen-specific CD4+ and CD8+ T cells." (PMID 35640930, 2022). "In fact, while CD8 lymphocytes are considered to be main tumor cell killers, among the CD4+ T helper subsets, the cells of type 2 (Th2) may dominate in tumors." (PMID 35158957, 2022). "In addition, DFNA5 expression had pronounced association with tumour purity and enrichment of immune cells, including B cells, CD8 + T cells, macrophages, CD4 + T cells, dendritic cells, neutrophils in LUAD." (PMID 35248047, 2022). "TLR8 signaling could reverse the suppressive functions of tumor-derived CD4+ T cells, CD8+ T cells and γδ regulatory T (Treg) cells resulting in enhanced anti-tumor immunity." (PMID 35413927, 2022). "Moreover, NLRC4/NAIP5 also participated in the antigen recognition of flagellin-expressing tumor cells to facilitate antigen presentation to T cells, thereby activating CD4+ and CD8+ T cells and exerting antitumor effects." (PMID 35928454, 2022). "Therefore, further mechanistic in vitro and in vivo studies of activin in the context of AEG/ASs, especially with regards to its effect on CD4+ tumor infiltrating lymphocytes, are warranted." (PMID 36064338, 2022). "In addition, high expression of NCAPG correlated with tumor infiltration of B cells, CD4+ T cells, CD8+ T cells, neutrophils, macrophages, and dendritic cells." (PMID 35280743, 2022). "Indeed, activating effector CD8+ and CD4+ T cells in vitro in tumor-equivalent concentrations of lactic acid reduces their proliferation and capacity to produce cytokines." (PMID 35040434, 2022). "To determine whether Th2 polarization was required in CD4+ T cell immunity against breast carcinogenesis, we examined tumor development in K14-Tslptg, MMTV-PyMTtg, Il4r−/− (Tslp-PyMttg Il4rKO) in comparison to Tslp-PyMttg, PyMttg Il4rKO, and PyMttg animals." (PMID 35657353, 2022).
tumor (continued). "Historically, it was well acknowledged that cytotoxic CD8+ T cells take the front seat in mediating direct anti-tumor immune responses, while CD4+ T cells play important roles in promoting the activation, proliferation, differentiation and maintenance of CD8+ T cell pools." (PMID 35928827, 2022). "Effective therapeutic vaccination against tumors depends on the design and screening of a high-quality tumor antigen, efficient antigen uptake by DCs, the sustained activation of CD4+ T cells and CD8+ T cells, T-cell infiltration into the TME and the strong persistence of the immune response." (PMID 36477638, 2022). "Furthermore, a mechanism that tumour cells can adopt to evade the immune system is CD4+ T cell conversion, i.e., effector CD4+ T cells and naïve CD4+ T cells can be modulated by the milieu of the TME and be converted into Tregs or iTregs, respectively." (PMID 35406451, 2022). "Signal transduction was as follows: relevant research has discovered that in tumor immunity, CD4+ T cells can activate CD8+ T cells through a variety of mechanisms to differentiate into cytotoxic T lymphocytes (CTL), while maintaining and strengthening the antitumor response of CTL." (PMID 35340416, 2022). "Interestingly, we observed that the effects of BRB-E on Granzyme B production by CD8+ T cells were restricted to the primary tumor site, suggesting a potential link to BRB effects on CD4+ FoxP3+ Tregs in the tumor microenvironment." (PMID 36016924, 2022). "Furthermore, we found that BIRC5 was significantly correlated with the level of B cells, CD8+ T cells, CD4+ T cells, macrophages, neutrophils and dendritic cells, and was negatively correlated with tumor purity." (PMID 35309512, 2022). "Thus, we found that numbers of CD8+ T cells in tumor samples were generally higher than those in normal tissue in PTC-WO and PTC-W, but the numbers of CD4+ T cells were similar in tumor and normal samples." (PMID 35720279, 2022). "This study suggested that this tumour infiltration with CD4+ T cells occurred via CTLA-4 expressed on regulatory T cells interacting with CD80-expressing dendritic cells present in peritumoral lymph nodes, thus demonstrating a role for CTLA-4/CD80 interaction in T-cell exclusion." (PMID 35626020, 2022). "A balanced ratio of CD8+ T cells to CD4+ T cells is beneficial for anti-tumor efficacy." (PMID 35203517, 2022). "Similarly, CIITA-expressing DFT cells have the potential to present MHC-II-restricted tumour antigens to CD4+ T cells and potentiate anti-DFT immune responses." (PMID 36259237, 2022). "In order for this to occur CD4 responses need to recognize antigen in the tumour environment." (PMID 36544781, 2022). "Additionally, CD4+ T helper cells proved to have an essential role in the anti-tumor immunity by responding to antigens presented by antigen-presenting cells (APCs) such as macrophages." (PMID 36072957, 2022). "Therefore, we assumed that the reason that Group A had more cases with positive PD‐L1 expression or positive CD4+ and FoxP3+ lymphocytes on tumor cell clusters was because of the immune reaction system occurred." (PMID 35137571, 2022). "With a known critical role of CD4+ T cells in cancer immunity, we reasonably speculate that the different percentages of CD4+ T cells will ultimately determine the capacity of CIKs in killing tumor cells." (PMID 35523765, 2022). "Interestingly, PeptiCRAd1 showed higher CD8+/CD4+ T-cell ratio within the TME of the treated tumor (right side) well in line with an increased CD8+ T-cell infiltration in both treated (right side) and untreated (left side) cancer lesions." (PMID 35314027, 2022). "In addition, the proportions of CD8+ T cells, CD4+ T cells, MDSCs, NK cells and macrophages were also increased in the tumour tissue in the SEPT5 knockdown group compared with the control group (p < 0.05)." (PMID 36439885, 2022). "Conversely, there were less resting memory CD4 cells in the tumor tissues." (PMID 35702258, 2022).